ITGB1 (integrin subunit beta 1)
Diseases named in the same sentence as ITGB1 in open-access papers (continued):
Sharing a sentence is not in itself a finding about the gene and the disease.
ovarian carcinoma (41 papers, 2007 to 2025). A malignant neoplasm originating from the surface ovarian epithelium. "Meanwhile, higher mRNA expression of ITGA3 and ITGB4/8 were significantly associated with poor PFS, lower mRNA expression of ITGA4/A6/A7/A10/AX and ITGB1 were significantly associated with poor PFS in ovarian cancer patients." (PMID 32765584, 2020). "Increased expression of ITGB1 was associated with drug resistance in ovarian cancer cells." (PMID 32565741, 2020). "In ovarian cancer cells in which ITGB1 is knocked down, it reduced COL1A1-induced metastasis by partially suppressing the phosphorylation of AKT." (PMID 38963646, 2025). "Survival analysis of the TCGA ovarian cancer cohort revealed that higher expression levels of TIMP3, BRAF, and ITGB1 were significantly associated with poorer overall survival." (PMID 41294900, 2025). "For instance, previous study identified integrin-β1 (ITGB1) as a direct target of miR-6126 in ovarian cancer." (PMID 40959569, 2025). "Collectively, this study defines a core regulatory axis—miR-192-5p/ITGB1/TIMP3/BRAF—that underpins differences in ovarian cancer progression and patient survival." (PMID 41294900, 2025). "ALKBH5 has been recently reported to induce lymphatic metastasis in ovarian cancer by regulating ITGB1 expression, and antibodies that block ITGB1 are promising anti-metastatic agents." (PMID 38254031, 2024). "ITGB1 was thought to control tumor cell metastasis; however, its role in ovarian cancer cell migration was unclear." (PMID 36632222, 2023). "Specifically, SPP1-ITGB1 was previously shown to promote progression in ovarian cancer via the ITGB1/FAK/AKT signalling pathway." (PMID 37370765, 2023). "For instance, miR-200c, a member of the miR-200 family, inhibits the epithelial–mesenchymal transition (EMT) and reduces the invasive potential of ovarian cancer cells, at least in part through ITGB1 downregulation." (PMID 37760437, 2023). "The miR-200 family has been reported to suppress the metastasis of ovarian cancer by downregulating integrin β1 (ITGB1)." (PMID 37760437, 2023). "In conclusion, we have identified that DDR2-expressing CAFs regulate POSTN through ITGB1 to promote tumor metastasis in ovarian cancer." (PMID 35884543, 2022). "ITGB1 down‐regulation was also reported to diminish the role of TGF‐β action on ovarian cancer cells." (PMID 33073486, 2020). "The increased expression of ITGB1 was also observed in other tumors, such as prostate cancer, ovarian carcinoma, lung cancer, colorectal adenocarcinomas, and in triple negative breast cancer." (PMID 33014056, 2020). "Inhibition of ITGB1 also attenuates the tumorigenesis of ovarian cancer cells and contributes to bevacizumab anticancer therapy through focal adhesion signalling pathway." (PMID 33073486, 2020). "We found that ITGB1 siRNA co-transfection with HULC reversed the function of HULC in inducing ovarian cancer cell migration and invasive ability." (PMID 29022892, 2017). "In ovarian cancer cells, we used two distinct siRNAs to knock down ITGB1 expression." (PMID 36632222, 2023). "Similarly, miR-29b targets and downregulates ITGB1, leading to the inhibition of metastasis and invasion of ovarian cancer cells." (PMID 37760437, 2023). "High ITGB1 expression enhances the invasiveness of ovarian cancer cells." (PMID 33335550, 2020). "In ovarian cancer, increased ITGB1 enhanced metastasis by mediating ECM remodeling." (PMID 32232000, 2020). "This may partly explain the correlation between reduced RFS and ITGB1 overexpression in ovarian cancer patients revealed by our data." (PMID 32565741, 2020). "Therefore, we hypothesised that ITGB1 also induced LN metastasis in ovarian cancer through a similar mechanism." (PMID 36632222, 2023). "Moreover, si-ITGB1 co-transfection with HULC inhibited the tumor-promoting effect of HULC by inhibiting tumor metastasis and invasion, suggesting that HULC may promote ovarian cancer progression by regulating ITGB1." (PMID 29022892, 2017).
ovarian carcinoma (continued). "The gene–pathway enrichment heatmap and DepMap analyses collectively emphasize ITGB1, TIMP3, and BRAF as central molecular hubs in ovarian cancer biology." (PMID 41294900, 2025). "The mRNA levels of ITGA1, ITGB1, ITGB3, and ITGB8 were found to be highly elevated in ovarian cancer tissues compared to those in normal ovarian tissues." (PMID 37596406, 2023). "Expression of ITGA5 and ITGB1 inversely correlated with disease-free survival in pancreatic, but not breast, lung, or ovarian cancer." (PMID 37563605, 2023). "In ovarian cancer, FOXM1 also induces the expression of integrins and matrix proteins: ITGB1, ITGAV, ITGA5, LMNB1, and FN1, which may facilitate adhesion of ovarian cancer cells to new organs." (PMID 34205406, 2021). "For example, miR-17 suppresses peritoneal metastasis in ovarian cancer through ITGA5 and ITGB1." (PMID 33024414, 2020). "The objective of this study demonstrates that HULC may promote ovarian carcinoma tumorigenesis by inhibiting ATG7 and induce progression by regulating ITGB1." (PMID 29022892, 2017). "Taken together, our results show that HULC may promote ovarian carcinoma tumorigenesis by inhibiting ATG7 and inducing progression by regulating ITGB1." (PMID 29022892, 2017). "Following HULC siRNA transfection of ovarian cancer cells, ATG7, LC3 and LAMP1 mRNA and protein expression both were significantly higher than in the control, whereas expression of SQSTM1 and ITGB1 was significantly decreased by HULC siRNA transfection compared with the negative control (P<0.05)." (PMID 29022892, 2017).
pancreatic cancer (40 papers, 2012 to 2025). "FN1 and ITGB1 not only play a role in pancreatic cancer, but also be closely associated with overall survival, immune cell infiltration, tumor mutation burden and microsatellite instability in pan-cancer." (PMID 35979350, 2022). "By combination of results from expression, survival and correlation analysis demonstrated that MMP9/ITGB1-miR-29b-3p-HCP5 competing endogenous RNA (ceRNA) sub-network was linked to prognosis of pancreatic cancer." (PMID 31061236, 2019). "A study by Oklahoma University suggested that ZIP4 could increase the resistance of pancreatic cancer patients to gemcitabine by upregulating the expression of ITGB1, which was associated with a poor prognosis." (PMID 35979350, 2022). "Knockdown of NNT‐AS1 reduced ITGB1 expression and growth of pancreatic cancer cell lines, but overexpression of ITGB1 restored growth of pancreatic cancer cell lines even when NNT‐AS1 was knocked down." (PMID 40448344, 2025). "It was found that overexpression of ITGB1 was significantly associated with advanced AJCC stage, histological grading, and poorer prognosis in pancreatic cancer patients." (PMID 38402311, 2024). "The influence of CAFs on clonal proliferation was significantly reduced when ITGB1/FAK signaling was inhibited in pancreatic cancer cells." (PMID 38279122, 2024). "As to the predicted immune functions of ITGB1, it has been proven to promote immune escape in pancreatic cancer under the regulation of METTL3-mediated N6-methyladenosine (m6A) modification." (PMID 38814534, 2024). "ITGB1 has been identified as an oncogene, and ITGB1 has been shown to promote the development of various cancers, including pancreatic cancer, gliomas, and cervical cancer." (PMID 39143438, 2024). "MiR-760 and miR-199a-5p also downregulated ITGB1 indirectly, the former downregulating MOV10 mRNA, an RNA-binding protein that stabilizes ITGB1 mRNA (the miRNA acting as an anti-proliferative/pro-apoptotic TSG in pancreatic cancer)." (PMID 36512308, 2023). "FN1 and ITGB1 can inhibit immune T cell activition by upregulation of macrophages and neutrophils, thereby leading to immune escape of pancreatic cancer cells and reducing the response rate of ICI treatment." (PMID 35979350, 2022). "In the ITGB1 high-expression groups, the prognosis of pancreatic cancer, along with lymph node metastasis, T factor, and tumor markers, was significantly worse (p = 0.035)." (PMID 35648752, 2022). "The upregulation of PODXL and ITGB1 in surgically resected pancreatic cancer tissues is correlated with an unfavorable postoperative prognosis." (PMID 35275973, 2022). "It is expected that ITGB1 will contribute to markers and treatment in pancreatic cancer if the development, research, and clinical application of these drugs progress in the future." (PMID 35648752, 2022). "The same is true for pancreatic cancer, and a few studies reported that high protein and gene expression of ITGB1 is positively correlated with a poor cancer prognosis." (PMID 35648752, 2022). "Compared with TNM staging, ITGB1 overexpression has been reported to predict a poor prognosis of pancreatic cancer." (PMID 36178365, 2022). "In pancreatic cancer, it has been reported that high expression of ITGB1 is involved in the migration of cancer cells, and that high expression of ITGB1 and ITGA3 confers resistance to gemcitabine by increasing integrin α3β1 signaling." (PMID 35648752, 2022). "We also identified FN1 and ITGB1 as core genes in the m7Gscore model, which affect immune cell infiltration and genomic instability not only in pancreatic cancer but also in pan-cancer." (PMID 35979350, 2022). "It has been reported that high ITGB1 expression significantly correlated with the deterioration of prognosis in colorectal, breast, and lung cancers, but its correlation with pancreatic cancer remains controversial." (PMID 35648752, 2022).
pancreatic cancer (continued). "Bioinformatics analysis of RNA sequencing data identified ITGB1 (Integrin beta 1) as an important gene for pancreatic cancer metastasis, progression, and prognosis." (PMID 35648752, 2022). "In pancreatic cancer, some reports indicated that ITGB1 is distributed as α2β1 and α5β1 in tumor cells and binds to the basement membrane and extracellular matrix." (PMID 35648752, 2022). "Using transcriptome analysis of pancreatic cancer tissues, we confirmed ITGB1 to be an independent prognostic factor in pancreatic cancer." (PMID 35648752, 2022). "Bioinformatics analysis of RNA sequencing data for pancreatic cancer identified ITGB1 as an important hub gene." (PMID 35648752, 2022). "Immunohistochemistry was performed using anti-PODXL and anti-ITGB1 antibodies on 24 pancreatic cancer tissue samples preoperatively obtained by endoscopic ultrasound-guided fine-needle aspiration biopsy." (PMID 35275973, 2022). "In pancreatic cancer, ITGB1 promotes gemcitabine resistance via CDC42 activation of PI3K p110β signalling." (PMID 33613118, 2021). "Immunohistochemistry was performed using an anti-ITGB1 antibody on 102 samples of pancreatic cancer tissue surgically resected at the University of Kochi Medical School Hospital and the Matsuyama Shimin Hospital." (PMID 31166991, 2019). "Taken all the three levels into consideration, we constructed a novel mRNA-miRNA-lncRNA triple sub-network, MMP9/ITGB1-miR-29b-3p-HCP5, which is significantly associated with prognosis of pancreatic cancer." (PMID 31061236, 2019). "Anti-tumor miR-124-3p regulates important intracellular pathways for pancreatic cancer via dual ITGA3/ITGB1." (PMID 29988949, 2018). "In cell culture studies, ITGB1 has been shown to play a critical role in pancreatic cancer progression and in metastasis in particular." (PMID 22925330, 2012). "In pancreatic cancer, HLA‐B modulates ITGB1 expression, influencing migration and transmembrane signaling, while its altered expression impairs tumor antigen recognition in cervical cancer and affects immune checkpoint inhibitor efficacy in gastrointestinal malignancies." (PMID 41316520, 2025). "In pancreatic cancer, HLA-B regulates ITGB1 in opposing ways in various cell lines." (PMID 38279122, 2024). "Another interesting study conducted by Shibata and colleagues found that pancreatic cancer-derived EVs carry adipocyte-targeting integrins, integrin subunit beta 1 (ITGB1) and integrin subunit alpha 6 (ITGA6), that aid in inducing lipolysis during pancreatic cancer-associated cachexia." (PMID 37998333, 2023). "Examination of the relationship between gene expression and prognosis using the R2 platform showed that ITGB1 was significantly correlated with the prognosis of pancreatic cancer (p = 0.036), but COL4A1 (p = 0.084), COL4A2 (p = 0.121), and ITGA5 (p = 0.285) were not." (PMID 35648752, 2022). "Finally, we concluded that FN1 and ITGB1 can also up-regulate macrophages and neutrophils and inhibit immune T cell activition in pancreatic cancer, leading to immune escape and reducing the response rate of ICIs treatment." (PMID 35979350, 2022). "Our findings suggest that a high ITGB1 expression could predict the prognosis and recurrence of pancreatic cancer." (PMID 35648752, 2022). "In addition to local effects of integrin expression on tumor cells, detection of ITGB1 in tumor exosomes was shown to provide a premetastatic niche for lung metastases in pancreatic cancer." (PMID 36456612, 2022). "The aim of this study was to investigate whether PODXL and ITGB1 are useful preoperative markers for the prognosis of postoperative pancreatic cancer patients in comparison with the TNM staging system." (PMID 35275973, 2022). "We identified ITGB1 as an important gene in the progression of pancreatic cancer." (PMID 35648752, 2022). "Integrin-targeted treatment may facilitate the treatment of pancreatic cancer, as ITGB1 has been reported to inhibit cell proliferation, infiltration, and migration in pancreatic cancer." (PMID 35648752, 2022).
pancreatic cancer (continued). "Therefore, we conclude that FN1 and ITGB1 can lead to immune evasion in pancreatic cancer and reduce the response rate of ICIs by up-regulating the activity of macrophages and neutrophils, and down-regulating expression of immune T cells." (PMID 35979350, 2022). "Multivariate analysis demonstrated TNM stage and the combination of PODXL with ITGB1 to be correlated with postoperative survival, and the combination of PODXL with ITGB1 most accurately predicted the postoperative outcomes of pancreatic cancer patients before resection." (PMID 35275973, 2022). "All the following factors—ITGB1 expression, CA19-9, operation time, operation type, bleeding volume, vascular invasion, neural invasion, lymph node metastasis, tumor diameter, and T factor—were significantly associated with poor prognosis of pancreatic cancer." (PMID 35648752, 2022). "Moreover, the miR-760/MOV10/ITGB1 pathway was important for the sensitivity of cells to the chemotherapy drugs in pancreatic cancer." (PMID 33456356, 2021). "The aim of this study was to investigate the use of PODXL, BCL7B, ARHGEF4, and the integrin family member ITGB1 as useful markers for the prognosis of postoperative pancreatic cancer patients in comparison with tumor size and the tumor node metastasis (TNM) staging system." (PMID 31166991, 2019). "For example, MMP9 participated in pancreatic cancer angiogenesis and invasion; CXCL8 promoted invasiveness and angiogenesis in pancreatic cancer; ITGB1 was upregulated in pancreatic cancer and increased ITGB1 indicated a poor outcome; and STAT1 enhanced pancreatic cancer growth and metastasis." (PMID 31061236, 2019). "We believe that ITGB1 may be used as a drug target for pancreatic cancer in the future." (PMID 35648752, 2022). "Therefore, upregulation of PODXL and ITGB1 may indicate preoperative neoadjuvant therapy for pancreatic cancer patients by accurately predicting the postoperative prognosis." (PMID 35275973, 2022). "lncRNA NNT‐AS1 is highly expressed in pancreatic cancer by HIF‐1α‐mediated transcription, and m6A‐modified NNT‐AS1 by METTL3‐HuR stabilizes ITGB1." (PMID 40448344, 2025). "These ALDH+ CSCs have higher levels of the ITGB1-FAK expression, and additional FAK inhibition can prevent the formation of clonogenic pancreatic cancer cells both in vitro and in vivo." (PMID 38279122, 2024). "ITGB1 and ITGA6 present on pancreatic cancer-derived EVs were found to control the EV tropism toward adipocytes where these EVs stimulate lipolysis via the cyclic adenosine monophosphate (cAMP)-PKA)-HSL pathway." (PMID 37998333, 2023). "Previous studies have found that ITGB1 inhibits radiosensitivity and enhances DDR in head and neck squamous cell carcinoma, pancreatic cancer and lung cancer." (PMID 37449209, 2023). "Although previous data reported that H19 overexpression reduced ITGB3, ITGB5, and ITGA5 in bladder cancer cells and increased ITGB1 and ITGA1 in pancreatic cancer cells, the molecular mechanism by which H19 regulates integrin was not elucidated." (PMID 31426484, 2019). "KH‐type splicing regulatory protein (KHSRP) binds to and stabilizes m6A of the met proto‐oncogene, receptor tyrosine kinase (MET), integrin subunit alpha v (ITGAV), and integrin subunit beta 1 (ITGB1) mRNAs, activating the FAK signaling pathway and promoting pancreatic cancer growth." (PMID 40448344, 2025). "For example, in pancreatic cancer, the ITGB1-driven Src-AKT pathway, which is independent of EGFR signaling, enhances resistance to cetuximab therapy." (PMID 40685383, 2025). "Furthermore, on the pairwise colocalization effect of CD29 with HLA-ABC, certain isotypes of HLA-B are able to decrease ITGB1 expression and affect pancreatic cancer cell migration with contrasting effects." (PMID 38983848, 2024).
pancreatic cancer (continued). "Our current study identified the change of exosome and lipid metabolism-related genes with clinical value, and the 7-gene (ABCB1, CAP1, EGFR, ITGB1, MAPK1, PPARG, SNCA) prognostic formula is a novel and reliable predictive index in pancreatic cancer and other multiple cancers." (PMID 37857015, 2023). "It has been demonstrated that MSA can induce entosis in pancreatic cancer cells by cell detachment via the downregulation of two important factors: the cell division control protein 42 homolog (CDC42) and its downstream effector integrin-β1(ITGB1, CD29)." (PMID 36144278, 2022). "The analytic results demonstrated that 7 upregulated (MMP9, CXCL8, ACTB, ITGB1, STAT1, TOP2A and CDK1) and 2 downregulated (GNMT and ABAT) hub genes may act as the key genes in pancreatic cancer." (PMID 31061236, 2019). "It is notable that the combination of PODXL with ITGB1 and the combination of BCL7B with ITGB1 accurately predicted the postoperative outcomes of pancreatic cancer patients with or without adjuvant therapies." (PMID 31166991, 2019).